TRMT61A (tRNA methyltransferase 61A)
Description:
Catalytic subunit of tRNA (adenine-N(1)-)-methyltransferase, which catalyzes the formation of N(1)-methyladenine at position 58 (m1A58) in initiator methionyl-tRNA. Catalytic subunit of mRNA N(1)-methyltransferase complex, which mediates methylation of adenosine residues at the N(1) position of a small subset of mRNAs: N(1) methylation takes place in tRNA T-loop-like structures of mRNAs and is only present at low stoichiometries.
Synonyms: C14orf172; TRM61; FLJ40452; GCD14; Gcd14p; hTRM61
Tractability: Small molecule: a structure with a bound ligand is known. PROTAC: ubiquitination databases record sites on it; its protein half-life has been measured.
Gene: Protein-coding gene on chromosome 14 (103,521,582 to 103,537,073, forward strand). Ensembl gene ENSG00000166166.
Subcellular location: Nucleus
Subcellular location (Human Protein Atlas): Mitochondria
Pathways (Reactome):
Metabolism of RNA: tRNA modification in the nucleus and cytosol
Gene Ontology:
Molecular function: mRNA (adenine-N1-)-methyltransferase activity; protein binding; tRNA (adenine(58)-N1)-methyltransferase activity
Biological process: mRNA processing; tRNA methylation; RNA processing
Cellular component: tRNA (m1A) methyltransferase complex; nucleoplasm; nucleus
Genetic constraint (gnomAD): Loss-of-function variants: 15 observed, 19.52 expected, observed/expected ratio (o/e) 0.77, 90% interval 0.51 to 1.18. The upper end of that interval is the gene's LOEUF score, 1.18, which puts it in group 5 of 6, group 1 being the genes least tolerant of losing a copy. Missense variants: 352 observed, 405.03 expected, observed/expected ratio (o/e) 0.87, 90% interval 0.8 to 0.95. Synonymous variants: 183 observed, 179.08 expected, observed/expected ratio (o/e) 1.02, 90% interval 0.9 to 1.15.
Homologues: Orthologues: chimpanzee TRMT61A (100% identical), macaque TRMT61A (99% identical), dog TRMT61A (96% identical), rabbit TRMT61A (96% identical), pig TRMT61A (94% identical), guinea pig TRMT61A (94% identical), rat Trmt61a (92% identical), mouse Trmt61a (91% identical), zebrafish trmt61a (70% identical), tropical clawed frog trmt61a (69% identical), Drosophila melanogaster Trmt61 (52% identical), Caenorhabditis elegans W02A11.1 (46% identical). Paralogues in human: TRMT61B (20% identical).
Diseases named in the same sentence as TRMT61A in open-access papers:
TRMT61A is named in the same sentence as 21 diseases in open-access papers, as found by Europe PMC text mining. Sharing a sentence is not in itself a finding about the gene and the disease. The quoted sentences say what the papers report.
hepatocellular carcinoma (9 papers, 2021 to 2026). A malignant tumor that arises from hepatocytes. "tRNA methyltransferase 6 (TRMT6) and TRMT61A are implicated in the initiation of glioma, gastrointestinal cancer, and hepatocellular carcinoma (HCC)." (PMID 37531210, 2023). "High expression of m1A-related regulators (m1A writer TRMT6, TRMT61A, and eraser ALKBH3) was associated with poor prognosis in several cancers, including hepatocellular carcinoma, colon cancer, glioma, breast cancer, and ovarian cancer." (PMID 38655053, 2024). "Additionally, TRMT6 and TRMT61A have been implicated in glioma, gastrointestinal cancer, and hepatocellular carcinoma (HCC) development." (PMID 38408075, 2024). "The study showed that the m1A methyltransferase complex (TRMT6 and TRMT61A) could increase PPARδ translation, which in turn triggers cholesterol synthesis to activate Hedgehog signaling in human hepatocellular carcinoma cell lines." (PMID 36035160, 2022). "In hepatocellular carcinoma (HCC), the methyltransferase complex formed by TRMT61A and TRMT6 is highly expressed, leading to a significant increase in the m1A methylation of tRNA, especially on tRNAAla (AGC) and tRNAGlu (CTC)." (PMID 41501031, 2026). "In glioma, glioblastoma, and hepatocellular carcinoma, overexpression of TRMT6/TRMT61A promotes proliferation and malignant transformation." (PMID 38304034, 2023). "For instance, the expression of TRMT6/TRMT61A is significantly increased in hepatocellular carcinoma tissues and increased TRMT6 and TRMT61A levels are negatively associated with patient prognosis (Wang YY." (PMID 38482382, 2024).
glioma (7 papers, 2021 to 2024). A benign or malignant brain and spinal cord tumor that arises from glial cells (astrocytes, oligodendrocytes, ependymal cells). "In addition to TRMT61A, the expression of other m1A regulators was associated with overall survival (OS) in glioma." (PMID 35936006, 2022). "The expression of HAVCR2, PVR, TNFRSF25, and TNFSF15 showed a positive correlation with the expression of numerous MRM-related genes like GTPBP3, METTL2A, METTL6, METTL8, NSUN4, and TRMT61A in glioma cells." (PMID 38824202, 2024). "Kaplan–Meier survival curves showed that overexpression of TRMT61B, TRMT6, TRMT61A, YTHDFs, ALKBH1, and ALKBH3 was significantly associated with poor overall survival in glioma." (PMID 34631793, 2021). "Then we found that overexpression of TRMT61B, TRMT6, TRMT61A, YTHDFs, ALKBH1, and ALKBH3 was significantly associated with poor overall survival in glioma." (PMID 34631793, 2021). "In glioma cells, it was observed that the expression of genes related to MRM, like GTPBP3, METTL2A, METTL6, METTL8, NSUN4, and TRMT61A, showed positive correlation with the expression of HAVCR2, PVR, TNFRSF25 and TNFSF15 as revealed by scRNA-seq analysis." (PMID 38824202, 2024).
bladder cancer (3 papers, 2023 to 2025). "For example, the expression of TRMT61A was significantly upregulated in bladder cancer cell lines compared to SV-HUC-1 cells." (PMID 40416872, 2025). "Studies have confirmed that TRMT6/61A is abnormal in bladder cancer cells, and silencing the expression of TRMT61A in bladder cancer cells can inhibit cell proliferation and invasion and promote cell apoptosis." (PMID 36707905, 2023).
glioblastoma multiforme (3 papers, 2023 to 2024). "In highly aggressive glioblastoma multiforme, unlike Grade II/III glioblastomas, a significant upregulation in TRMT6/TRMT61A expression was noted." (PMID 38943267, 2024).
Cornelia de Lange syndrome (1 paper, 2025). A rare syndrome characterized by low birth weight, delayed growth, intellectual disabillity, behavioral problems, and a distinctive facial appearance (thin, arched eyebrows, low set ears, small teeth, and small nose). "Cornelia de Lange Syndrome (CdLS) also exhibits autism-related features, such as impairments in verbal communication and a genetic abnormality involving TRMT61A protein mislocalization, ultimately affecting normal mitochondrial function." (PMID 40867184, 2025).
dysplasia (1 paper, 2024). A usually neoplastic transformation of the cell, associated with altered architectural tissue patterns. "We investigated TRMT61A expression by IHC in HNSCC tissue microarrays comprising 42 oral mucosa, 69 dysplasia, and 210 HNSCC samples." (PMID 38730256, 2024).
intestinal infection (1 paper, 2026). "This study establishes that TRMT61A expression in ILC3s is crucial for defending against intestinal infection and inflammation." (PMID 41484094, 2026).
liver cancer (1 paper, 2021). An epithelial or non-epithelial malignant neoplasm that arises from the liver. "Altogether, thiram acts as an efficient inhibitor against TRMT6/TRMT61A complex that effectively inhibits tumor growth of liver cancer." (PMID 34728628, 2021). "Finally, we identify a potent inhibitor against TRMT6/TRMT61A complex that exerts effective therapeutic effect on liver cancer." (PMID 34728628, 2021).
neuroendocrine disorder (1 paper, 2023). A disease or disorder that affects the neuroendocrine gland, any of the organized aggregations of cells that function as secretory or excretory organs and that release hormones in response to neural stimuli. "Overall, the causal effect may involve two pathophysiological pathways, including glucose metabolism (PPM1K and TRMT61A) related to plaque progression and the newly discovered neuroendocrine disorders (CBLN1, MRPL33, and C2orf16) related to plaque rupture and thrombosis." (PMID 36984843, 2023).
cancer (12 papers, 2021 to 2026). A tumor composed of atypical neoplastic, often pleomorphic cells that invade other tissues. "Analysis of m1A-associated genes identified TRMT61A as a key m1A writer linked to cancer progression and poor prognosis." (PMID 38730256, 2024). "TRMT61A is positively associated with Reptin as an m1A writer in 35 types of cancer, and ALYREF, as the m5C reader, was positively associated with Reptin in 35 cancer types." (PMID 35754815, 2022). "Cancers overexpressing TRMT61A may be especially susceptible to thiram treatment." (PMID 38730256, 2024). "Using the four-gene signature (YTHDF3, RBM15B, IGF2BP2, and TRMT61A), we constructed a nomogram to estimate 1-year and 3-year overall survival probabilities in patients from the eight selected TCGA cancer types." (PMID 40565233, 2025). "Together, these findings identified TRMT61A as a key m1A regulator in cancer, warranting further study." (PMID 38730256, 2024). "Our previous results suggested that TRMT61A is highly expressed in BLCA, indicating that TRMT61A functions as a cancer-promoting gene in BLCA." (PMID 38482382, 2024). "Taken together, these results provide evidence supporting the role of TRMT61A in promoting cancer stemness and epithelial-mesenchymal transition." (PMID 38730256, 2024). "Further analysis revealed upregulated TRMT61A mRNA in various human cancers, including liver, breast, and colon." (PMID 38730256, 2024). "Reculstering of IFNγ pathway genes showed a shifted expression profile in the IFNγ pathway in sh61A CAL 27 cells, with pronounced downregulation of CD274 and CD47, reinforcing the conclusion that TRMT61A is critical to the reactive upregulation of PD-L1 on cancer cells during inflammation." (PMID 38730256, 2024). "Encouraged by promising in vitro results, we speculated therapies suppressing TRMT61A activity could restore immune responses against cancers during OV therapy." (PMID 38730256, 2024). "Since MYC positively regulates PD-L1 expression as a transcription factor, we hypothesize TRMT61A may play a role in OV therapy cancer immune evasion by promoting reactive PD-L1 expression through enabling efficient MYC synthesis." (PMID 38730256, 2024). "Dysregulation of TRMT6/TRMT61A has been reported in various cancers." (PMID 38304034, 2023). "In addition, TRMT61A may play a role in various cancers, such as testicular germ cell tumors, but its specific mechanism is still unclear and deserves further exploration." (PMID 41501031, 2026). "We speculate that TRMT61A suppression may restore antitumor immune responses in human cancers." (PMID 38730256, 2024). "Our data comprehensively delineate TRMT61A-mediated regulation of the MYC-PD-L1 signaling axis at the translational level, unveiling a novel mechanism governing cancer progression and immunotherapy response." (PMID 38730256, 2024). "The expression of m1A regulators has previously been investigated in various cancers, and upregulation of TRMT6, TRMT61A, and ALKBH3 has been reported in BLCA." (PMID 38304034, 2023). "ALKBH3 (p < 0.001), TRMT61A (p < 0.001), YTHDF1 (p < 0.001), ALKBH1 (p < 0.001), and TRMT6 (p < 0.001) in cancer tissues were significantly up-regulated compared to those in normal tissues (p < 0.001)." (PMID 34195072, 2021). "Additionally, TRMT61A modulates cholesterol biosynthesis and supports CD8+ T-cell responses, suggesting an intersection with tumor immunology in these cancers." (PMID 40565233, 2025). "Studies have shown that TRMT61A promotes cancer in CRC by activating the m1A-ONECUT2-SOS1-MAPK/ERK pathway, suggesting that targeting TRMT61A may offer a viable therapeutic strategy for CRC." (PMID 41446042, 2025).
tumor (11 papers, 2021 to 2026). "Using samples from BLCA patients, a positive correlation was observed between HMOX2 and TRMT61A expression; HMOX2 expression decreased in tumour tissues from mice xenografted with TRMT61A shRNA and increased in tumour tissues from BBN‐driven urinary BLCA mice." (PMID 39763068, 2025). "Western blot analysis showed that the expression of TRMT61A was significantly reduced in clinical HCC tumor samples compared to the normal paracancerous tissues." (PMID 40416872, 2025). "We propose high TRMT61A expression during tumor evolution increases PD-L1 expression, suppressing adaptive immune responses to promote tumor growth." (PMID 38730256, 2024). "Most importantly, dramatic upregulation of both TRMT6 and TRMT61A protein levels in tumor samples was detected by western blotting." (PMID 35444240, 2022). "We show m1A methyltransferase complexTRMT6/TRMT61A are elevated in HCC tumor tissues and liver CSCs." (PMID 34728628, 2021). "Abnormal expression of TRMT61A may lead tumor cells to escape immune surveillance and promote tumor progression." (PMID 41501031, 2026). "This suggests that TRMT61A inhibitors may serve as a novel strategy to enhance tumor immunotherapy and oncolytic virus therapy sensitivity." (PMID 40719884, 2025). "TRMT6/TRMT61A depletion reduced tumor growth of orthotopic xenografts." (PMID 34728628, 2021). "For example, TRMT61A-mediated tRNA-m1A modification regulates the synthesis of MYC protein, thereby influencing tumor cell proliferation." (PMID 40719884, 2025). "TRMT6 and TRMT61A, forming m1A methyltransferase complex, are highly expressed in advanced HCC tumours and are negatively correlated with HCC survival." (PMID 34728628, 2021). "Thiram displays effective suppression tumor growth in vivo, suggesting that thiram exerts its inhibitory antitumour effect through blockade of enzymatic activity of the TRMT6/TRMT61A complex." (PMID 34728628, 2021). "Together, these data indicate that TRMT6/TRMT61A-mediated m1A modification enhances PPARδ protein translation, and PPARδ promotes liver CSC self-renewal and tumor growth." (PMID 34728628, 2021). "In terms of mRNA levels, TRMT6, TRMT61A, TRMT61B, TRMT10C, YTHDF1 and YTHDF2 YTHDF3 were overexpressed in tumor sample." (PMID 34777359, 2021). "The results proved that ALKBH3 expression was lower in tumor compared to normal tissues, TRMT61A expression differences were not meaningful and the rest were expressed higher in OC." (PMID 34777359, 2021). "TRMT61A, TRMT61B, YTHDF1 and YTHDF3 mRNAs were higher in tumor tissues, but protein expression was weaker or not apparently distinct between tumor and normal samples." (PMID 34777359, 2021). "Notably, Mut-TRMT6/TRMT61A overexpression could not rescue TRMT6/TRMT61A enhanced tumor growth." (PMID 34728628, 2021).
bacterial infection (1 paper, 2026). "Further, to assess the function of ILC3-specific TRMT61A during bacterial infection, we infected mice with Citrobacter rodentium." (PMID 41484094, 2026).
infection (1 paper, 2026). The state of being infected such as from the introduction of a foreign agent such as serum, vaccine, antigenic substance or organism. "Post-infection, TRMT61A expression in ILC3s significantly increased, suggesting an active role in defending against C. rodentium." (PMID 41484094, 2026). "Our findings of increased Trmt61a expression in ILC3s following C. rodentium colonization suggest potential alterations in tRNA m1A58 modification, which could facilitate rapid protein synthesis crucial for ILC3 activation and proliferation during infection." (PMID 41484094, 2026).
TRMT61A also shares sentences with these, for which no sentence is quoted: Alzheimer disease (1 paper); breast carcinoma (1); colon cancer (1); digestive system neoplasm (1); glucose metabolism disorder (1); ovarian carcinoma (1); psychiatric disorder (1); thrombosis (1).